SATB2 (SATB homeobox 2)
Diseases named in the same sentence as SATB2 in open-access papers (continued):
Sharing a sentence is not in itself a finding about the gene and the disease.
neuroendocrine carcinoma (3 papers, 2022 to 2025). A malignant neuroendocrine neoplasm composed of cells containing secretory granules that stain positive for NSE and chromogranin. "In previous studies, SATB2 was described as an effective marker in the differential diagnosis of MCC and extracutaneous neuroendocrine carcinomas." (PMID 38066198, 2024). "In turn, among neuroendocrine carcinomas (NECs), a significant proportion of Merkel cell carcinomas (> 75%) express SATB2, which is positive in no more than a third of NECs of other sites." (PMID 35522392, 2022). "Low or absent SATB2 expression has been documented in the mucinous, micropapillary, medullary, and signet-ring CRC subtypes, and also in colorectal mixed adenoneuroendocrine carcinomas/neuroendocrine carcinomas (MANECs/NECs)." (PMID 40076993, 2025).
ovarian tumors (3 papers, 2019 to 2025). "Staining for SATB2 is useful in ovarian tumors with morphologic evidence of intestinal differentiation, or with expression of CDX2 or CK20, as most cases (98%) are typically negative." (PMID 31771640, 2019). "Ovarian tumors responsible for OPMP expressed PAX8 in 1/10 (10%) tumors, SATB2 in 3/10 (30%) tumors, CK7 in 6/12 (50%) tumors, and CK20 in 11/12 (91.7%) tumors." (PMID 38341381, 2024). "SATB2 is negative in most upper gastrointestinal and primary ovarian tumors, both benign and malignant." (PMID 40636692, 2025).
pancreatic adenocarcinoma (3 papers, 2014 to 2025). "While CDX2 appears to have somewhat higher sensitivity for CRC than SATB2, the previous studies have indicated that SATB2 has higher specificity for CRC, as CDX2 is frequently also expressed by adenocarcinomas of the pancreas or the upper gastrointestinal tract among others." (PMID 39998677, 2025).
signet ring cell carcinoma (3 papers, 2022 to 2024). A usually aggressive, poorly differentiated invasive adenocarcinoma characterized by the presence of malignant glandular cells in which the nucleus is pressed to one side by the presence of intracytoplasmic mucus. "Villin, CDX2, COX2, and SATB2 are specific markers derived from gastrointestinal adenocarcinoma, including signet ring cell carcinoma, and are often used to identify tumors from other systems, including the breast, lung, and the female reproductive system." (PMID 37337182, 2023). "The absence of CDX-2 (-), CK20 (-), CK7 (-), SATB2 (-), and PAS (-) rules out metastasis from signet ring cell carcinoma of the digestive system." (PMID 39723371, 2024).
Small cell osteosarcomas (3 papers, 2021 to 2025). "All stained cases were positive for SATB2 expression, which is believed to provide one of the key diagnostic clues to distinguish small cell osteosarcomas from other small round-cell malignancies of the bone." (PMID 35372059, 2022). "Small cell osteosarcomas have malignant osteoid and SATB2 positivity." (PMID 34722090, 2021). "Negative staining for special AT-rich sequence-binding protein 2 (SATB2) and the absence of osteoid matrix further assist in distinguishing ES from other small round cell malignancies, such as mesenchymal chondrosarcoma and small-cell osteosarcoma." (PMID 41589178, 2025).
adenocarcinomas of the urinary bladder (2 papers, 2025). "Notably, SATB2 is expressed in 49% of primary adenocarcinomas of the urinary bladder and 20% of urothelial carcinomas with glandular differentiation." (PMID 41321186, 2025).
Arthritis (2 papers, 2018 to 2021). Inflammation of a joint. "In ovariectomy (OVX) -induced bone loss and IL-1β-induced arthritis mice models, we examined SATB2 and TNF-α expression levels by immunohistochemistry using the antibodies specific for TNF-α and SATB2." (PMID 29435145, 2018). "We found that the SATB2 expression levels were negatively associated with the expression levels of TNF-α both in ovariectomy (OVX) -induced bone loss and IL-1β-induced arthritis animal models." (PMID 29435145, 2018). "SATB2 expression levels were negatively associated with the levels of TNF-α both in OVX-induced bone loss and IL-1β-induced arthritis mice." (PMID 29435145, 2018). "Given the interest in developing AP-1 inhibitors for treating cancer and inflammatory diseases such as arthritis, SATB2 could be a consequential target to pursue." (PMID 34686672, 2021). "In this study, we observed a negative correlation between TNF-α levels and the expression of special AT-rich sequence-binding protein 2 (SATB2), a critical osteoblastogenesis transcription factor, in ovariectomy (OVX)-induced bone loss and IL-1-induced arthritis animal model." (PMID 29435145, 2018). "In the current study, we are surprised to find that the expression of SATB2, a critical transcriptional node for osteoblast differentiation, is negatively associated with the levels of TNF-α in OVX-induced bone loss and IL-1β induced arthritis mice by immunohistochemistry." (PMID 29435145, 2018). "In IL-1β-induced arthritis mice, there were intense staining of TNF-α but weak staining of SATB2 in mature osteoblasts." (PMID 29435145, 2018).
Ataxia (2 papers, 2015 to 2021). Ataxia refers to impaired coordination of voluntary muscle movement. "In addition to Satb2-mediated hypersensitivity to sensory stimuli in our MiR34/449 mutant mice, we uncovered a series of neurological disorders—particularly staggering, ataxia, and seizure-like behaviors—that could not be fully accounted for by aberrant upregulation of Satb2 in the spinal cord." (PMID 33787491, 2021).
atherosclerosis (2 papers, 2023 to 2024). A disease characterized by the build-up of fatty material and calcium deposition in the arterial wall resulting in partial or complete occlusion of the arterial lumen. "Therefore, together, CUX1 and SATB2 fine‐tune the expression of p16INK4a via their competitive, but also coordinated binding to the atherosclerosis‐associated fSNP rs1537371, which precisely and tightly regulates cellular senescence in human ECs." (PMID 36633253, 2023). "Remarkably, we also demonstrate that IL‐1β, a senescence‐associated secretory phenotype (SASP) gene itself and a biomarker for atherosclerosis, induces cellular senescence also by upregulating CUX1 and/or downregulating SATB2 in human ECs." (PMID 36633253, 2023).
bone sarcoma (2 papers, 2020 to 2024). A sarcoma that arises from the bone. "The immunohistochemical analysis of MDM2, CDK4, and SATB2 in this case report was positive, indicating that this spindle cell sarcoma belongs to the category of bone sarcomas." (PMID 39634267, 2024).
bone tumors (2 papers, 2018 to 2025). "Intriguingly, SATB2 was documented to be a sensitive marker for bone tumors, especially osteosarcoma, which might serve as a practically, diagnostically or prognostically useful marker for bone tumors." (PMID 29435145, 2018).
carcinosarcoma (2 papers, 2025). A malignant tumor composed of a mixture of carcinomatous and sarcomatous elements. "Previous studies on the expression of SATB2 in the uterus have focused on endocervical adenocarcinomas, endometrial polypoid adenomyomas, uterine sarcomas, and carcinosarcomas." (PMID 41321186, 2025). "SATB2 was positive in 83% of low‐grade endometrial stromal sarcomas, 40% of undifferentiated sarcomas, 13% of leiomyosarcomas, 14% of adenosarcomas, and 8% of carcinosarcomas." (PMID 41321186, 2025).
celiac disease (2 papers, 2020 to 2025). An autoimmune genetic disorder with an unknown pattern of inheritance that primarily affects the digestive tract. "We observed that Crohn’s disease-associated SBAs were less frequently immunoreactive for SATB2 (12%) in comparison with sporadic (24%) or celiac disease-associated (25%) cases." (PMID 33228145, 2020). "We identified 20 SATB2-positive small bowel adenocarcinomas, including nine sporadic cancers, seven celiac disease-associated cancers and four Crohn’s disease-associated small bowel adenocarcinomas." (PMID 33228145, 2020). "SATB2-positive cases included nine Spo-SBAs, seven celiac disease-associated SBAs and four Crohn’s disease-associated SBAs." (PMID 33228145, 2020). "This is the first investigation of SATB2 expression in celiac disease-associated SBAs, reporting a 25% rate of positive cases." (PMID 33228145, 2020). "A CK7−/CK20+/CDX2+/SATB2+ pattern profile was present in three Crohn’s disease-associated SBAs, six Spo-SBAs and five celiac disease associated-SBAs." (PMID 33228145, 2020). "Nevertheless, up to now, only small SBA series, often including a very limited number of Crohn’s disease-associated SBAs (CrD-SBAs) and celiac disease-associated SBAs (CD-SBA), have been investigated for SATB2 expression." (PMID 33228145, 2020). "However, a fraction (up to 46%) of SBAs have been reported to exhibit SATB2 positivity, although studies on SATB2 expression in SBA are limited to relatively small series, which include very few SBAs associated with Crohn’s or celiac diseases." (PMID 33228145, 2020). "The prevalence of SATB2 positivity was lower in Crohn’s disease-associated SBAs (12%) in comparison with both celiac disease-associated (25%) or sporadic (24%) cases; however, the difference in the distribution of SATB2 expression amongst etiologic groups was not significant (p = 0.333)." (PMID 33228145, 2020). "Aberrant SATB2 expression and even a complete CRC-like immunoprofile may be observed in a fraction of SBAs, either sporadic or associated with immune-mediated intestinal conditions, in particular with celiac disease." (PMID 33228145, 2020). "Among them, there were two celiac disease-associated SBAs and four Spo-SBAs; worthy of note, none of the three Crohn’s disease-associated SBAs having a CK7−/CK20+/CDX2+/SATB2+ pattern expressed AMACR." (PMID 33228145, 2020).
cleft lip (2 papers, 2014 to 2019). Congenital defect in the upper lip where the maxillary prominence fails to merge with the merged medial nasal prominences. "Oral clefts are common in Thailand and genetic studies have demonstrated many genetic susceptibility loci and new mutations, including p63 which causes an isolated cleft lip, and SATB2 which causes a unique dysmorphic syndrome with intellectual deficit, SATB2-associated syndrome (SAS)." (PMID 24936510, 2014).
cleidocranial dysostosis (2 papers, 2020 to 2024). "In this context, repairing RUNX2 gene mutation in iPSCs derived from cleidocranial dysostosis patients as well as transducing nuclear matrix protein SATB2 and Alox5 gene into iPSCs promoted osteodifferentiation." (PMID 32300365, 2020). "In patients with cleidocranial dysplasia, a decrease in RUNX2 expression leads to upregulation of miR-31 and downregulation of SATB2 expression, resulting in reduced osteoclast differentiation and activity, ultimately causing delayed tooth eruption." (PMID 39834384, 2024).
Cluster headache (2 papers, 2022 to 2025). A type of headache characterized by repeated attacks of unilateral pain lasting 15 to 180 minutes and associated with local autonomic signs. "The four cluster headache susceptibility loci that were identified by this GWAS were rs113658130 near LINC01877/SATB2 (SATB homeobox 2), rs4519530 in MERTK, rs12121134 near LINC01705/DUSP10 (Dual Specificity Phosphatase 10), and rs11153082 in FHL5." (PMID 39560176, 2025). "Two of the identified loci (MERTK and SATB2) replicated the findings of the previous cluster headache GWAS conducted in European cohorts." (PMID 39560176, 2025). "We identified three susceptibility loci, in CAPN2, MERTK, and SATB2, as well as one suggestive locus at CYP2C18/CYP2C19 at genome-wide level in patients with cluster headache in Taiwan." (PMID 36404298, 2022). "We successfully replicated MERTK and SATB2 identified in previous cluster headache GWASs." (PMID 36404298, 2022).
colon adenocarcinoma (2 papers, 2020 to 2024). "The positive staining for SATB2 was confounding as that is typically associated with colonic adenocarcinomas." (PMID 39493029, 2024). "However, reduced SATB2 expression (similar to that of CDX2) has been reported in mismatch repair deficient colon adenocarcinomas and small intestinal cancers." (PMID 32867793, 2020). "Staining also showed weak SATB2 expression, a tumor marker specific to colonic adenocarcinomas, further complicating the picture." (PMID 39493029, 2024).
Crohn disease (2 papers, 2020 to 2022). A gastrointestinal disorder characterized by chronic inflammation involving all layers of the intestinal wall, noncaseating granulomas affecting the intestinal wall and regional lymph nodes, and transmural fibrosis. "However, two cases, both associated with Crohn’s disease, showed focal areas of SATB2-positive ileal epithelium, likely representing foci of metaplastic “colonic” phenotype of the ileal mucosa, which may occur in Crohn’s disease patients." (PMID 33228145, 2020). "Importantly, none of these six cases occur in Crohn’s disease patients, while the four SATB2-positive Crohn’s disease-associated SBAs were all AMACR-negative, suggesting that an aberrant full-blown CRC-like phenotype is extremely rare in SBAs arising in Crohn’s patients." (PMID 33228145, 2020). "Moreover, cancer-free ileal mucosa adjacent to two SATB2-negative Crohn’s disease-associated SBAs was seen to focally express SATB2." (PMID 33228145, 2020). "While Crohn’s disease-associated SBAs may rarely express SATB2, a full-blown CRC-like immunoprofile is virtually absent in such a specific subset." (PMID 33228145, 2020).
esophageal cancer (2 papers, 2025). A primary or metastatic malignant neoplasm involving the esophagus. "Bioinformatics analysis indicated that SATB2 is linked to increased drug resistance in esophageal cancer." (PMID 40078194, 2025). "To assess radioresistance in esophageal cancer following the stable downregulation of SATB2 in vivo, we developed a BALB/C-nu/nu nude mouse ESCC xenograft model." (PMID 40078194, 2025). "To investigate the impact of SATB2 on radioresistance in esophageal cancer cells, we developed radioresistant esophageal cancer cells (KYSE150R cells)." (PMID 40078194, 2025). "Consequently, this study aims to elucidate the mechanism by which SATB2 modulates radiotherapy resistance in esophageal cancer." (PMID 40078194, 2025). "In conclusion, our study reveals that overexpression of SATB2 can aberrantly activate the Wnt/β-catenin pathway, thereby inducing radioresistance and promoting EMT in esophageal cancer cells." (PMID 40078194, 2025).
intestinal tumors (2 papers, 2017 to 2025). "A growing number of researchers have begun to focus on SATB2 for its improved sensitivity over CDX-2 in intestinal tumors." (PMID 28969003, 2017).
liver cancer (2 papers, 2020 to 2024). An epithelial or non-epithelial malignant neoplasm that arises from the liver. "Using breast, pancreas, lung, colorectal and liver cancer models, we and others have demonstrated that silencing SATB2 expression by shRNA or Crisp/Cas9 significantly inhibited cell proliferation, and colony formation of various cancer cells." (PMID 32885593, 2020). "Higher expression of SATB2 gene has been reported in Merkle cell carcinoma, pancreatic, breast, colon, rectal and liver cancer patients than normal counterparts." (PMID 32885593, 2020).
Merkel cell carcinoma (2 papers, 2018 to 2024). "Therefore, the phenotype of Merkel cell carcinomas is CK7−/CK20+ (“dot-like”), CDX2−, SATB2+, Chromogranin+, Synaptophysin+ and positive for Merkel cell polyomavirus (MCPyV), while the phenotype of small cell carcinomas of the salivary glands is Synaptophin+, Chromogranin+/−, CD56+ and CDX2−." (PMID 29621151, 2018).
mesenchymal chondrosarcoma (2 papers, 2024 to 2025). A morphologic variant of chondrosarcoma arising from bone and soft tissue. "Of the tumors reclassified as mesenchymal chondrosarcomas (cases 14 and 16), CD99 was strongly positive in case 14, while SATB2, BCOR, and MUC4 were negative." (PMID 38332052, 2024).
oral cancer (2 papers, 2012 to 2023). "Until now, limited studies have been done to evaluate the relationship between SATB2 expression and cancer progression, such as colorectal, breast and oral carcinomas." (PMID 22815795, 2012). "A few studies have been done in colorectal, breast and oral carcinomas to evaluate the role of SATB2 in cancer, however, the results were highly controversial." (PMID 22815795, 2012).
orofacial cleft (2 papers, 2019 to 2022). A disorder of facial skeleton that is characterized by cleft lip and/or cleft palate that result in feeding, speech and hearing problems caused by failures during development. "The loss of SATB2 gene copy number in the family of affected cleft indicated the risk and susceptibility of SATB2 to cause orofacial cleft in the family trait." (PMID 30924295, 2019). "SATB2 is known to play a role in orofacial cleft particularly the cleft palate, involving the mutation at the chromosomal 2q32‐q33 region." (PMID 30924295, 2019). "As anticipated, absolute copy number loss of SATB2 in Family 50 and Family 100 was significantly attained in the family with affected members of nonsyndromic clefting compared to the normal individuals with no history of orofacial cleft." (PMID 30924295, 2019).
prostate carcinoma (2 papers, 2024 to 2025). A carcinoma that arises from epithelial cells of the prostate gland. "Further studies are needed to examine the oncogenic role of SATB2 in a transgenic mouse model of prostate cancer." (PMID 38891096, 2024). "We first compared the expression of SATB2 in human normal prostate epithelial cells (PrEC), prostate cancer cell lines (C4-2B, LNCaP, DU-145, and PC-3), and prostate CSCs using Western blot analysis and immunocytochemistry." (PMID 38891096, 2024). "Overall, our data suggest that the SATB2 gene acts as an oncogene in prostate cancer, and its expression alone is capable of inducing oncogenic transformation in vitro." (PMID 38891096, 2024). "In this study, we examined the oncogenic role of SATB2 in prostate cancer and assessed whether overexpression of SATB2 in human normal prostate epithelial cells (PrECs) induces properties of cancer stem cells (CSCs)." (PMID 38891096, 2024). "Overall, these data suggest that SATB2 alone is capable of inducing transformation of PrECs in vitro, and may have a role in prostate cancer initiation." (PMID 38891096, 2024). "The objective of this paper is to examine the oncogenic role of SATB2 in prostate cancer, and assess whether overexpression of SATB2 in PrECs gained the phenotypes of cancer stem cells (CSCs)." (PMID 38891096, 2024). "In the present study, SATB2 overexpression in PrECs promoted EMT, and its inhibition in prostate cancer stem cells (CSCs) suppressed/reversed EMT characteristics." (PMID 38891096, 2024). "The results demonstrate that SATB2 is highly expressed in prostate cancer cell lines and CSCs, but not in PrECs." (PMID 38891096, 2024). "In the present study, SATB2 is expressed in transformed cells, but not in normal prostate tissues, suggesting its use as a biomarker of prostate cancer." (PMID 38891096, 2024).
rectal NETs (2 papers, 2021 to 2022). "Ninety-six percent of rectal NETs are SATB-2 (special AT-rich sequence-binding protein 2) positive, but it is also frequently expressed in appendiceal NETs (79%)." (PMID 35626118, 2022).
rectal tumors (2 papers, 2012 to 2017). "As all rectal tumour samples were taken from post-treatment surgical specimens, it could be speculated that SATB2 levels are modified by neoadjuvant RT or chemotherapy." (PMID 22333599, 2012).